NF2 (NF2, moesin-ezrin-radixin like (MERLIN) tumor suppressor)
Diseases named in the same sentence as NF2 in open-access papers (continued):
Sharing a sentence is not in itself a finding about the gene and the disease.
neurofibromatosis type 2 (continued). "Neurofibromatosis type 2 (NF2) is an autosomal-dominant tumor predisposition syndrome caused by the inactivation of the NF2 gene located on chromosome 22q." (PMID 33803788, 2021). "Neurofibromatosis type 2 (NF2) is an autosomal dominant condition caused by pathogenic variants in the NF2 gene (NF2; MIM # 607379) causing loss of function of the tumor suppressor protein, Merlin." (PMID 33445724, 2021). "Four patients (2.2%) had tumors associated with a previously documented diagnosis of neurofibromatosis type 2 (NF2)." (PMID 33804061, 2021). "Mutations in NF2 causatively result in Neurofibromatosis type 2, an autosomal dominant disorder mainly associated with benign tumors in the nervous system, such as bilateral vestibular schwannomas, meningiomas, and ependymomas." (PMID 32299434, 2020). "Neurofibromatosis type 2 (NF2) is an autosomal-dominant tumor-prone disorder and caused by biallelic inactivation of the NF2 tumor-suppressor gene on the chromosome band 22q12." (PMID 32825434, 2020). "Neurofibromatosis Type 2- (NF2-) associated vestibular schwannomas (VSs) are histologically benign tumors." (PMID 32733557, 2020). "Loss of function mutations or deletions in NF2 cause Neurofibromatosis type 2 (NF2), a multiple tumor-forming disease of the nervous system." (PMID 32244473, 2020). "Well-known genetic alterations of meningiomas include monosomy 22 and inactivating mutations of NF2 gene that produces neurofibromin (also known as merlin), as seen in patients with Neurofibromatosis type 2 that develop multiple meningiomas." (PMID 32982948, 2020). "It is rare to find two or more primary intracranial tumors simultaneously in patients without previous radiation therapy or underlying phacomatosis such as Neurofibromatosis-2 (NF2)." (PMID 39931233, 2019). "Previous clinical reports found that mutated Nf2, a Hippo pathway regulator, leads to the development of cNF in neurofibromatosis type 2 patients." (PMID 31852972, 2019). "Patients with neurofibromatosis type 2 are predisposed to the development of ependymomas, and the gene for neurofibromatosis type 2 (NF2) maps to chromosome 22 (q1216,17)." (PMID 32612806, 2019). "Hearing-preserving partial resection of neurofibromatosis type 2 (NF2) associated vestibular schwannomas (VS) is a preferred treatment strategy, particularly for children and adolescents." (PMID 31769423, 2019). "More than half of all identified genomic alterations involve the neurofibromin gene (NF2), which is known to underlie inherited Neurofibromatosis syndrome." (PMID 31970090, 2019). "Neurofibromatosis type 2 (NF2) is a rare autosomal dominant genetic disorder caused by inactivating alterations in the NF2 gene on chromosome 22q12.2, with a prevalence of around 1 in 60,000." (PMID 31591325, 2019). "The efficacy of radiosurgery for neurofibromatosis type 2 (NF2)-associated vestibular schwannoma (VS) remains debatable." (PMID 31591325, 2019). "Neurofibromatosis type 2 (NF2) is an inherited tumor predisposition syndrome affecting 1 in 25,000 people, most of whom are germline heterozygous for the NF2 tumor suppressor gene." (PMID 29416648, 2018). "For instance, mutation of neurofibromin 2 (NF2) is a major reason for the development of neurofibromatosis type 2." (PMID 30453531, 2018). "Merlin (also known as Neurofibromin 2 or NF2) is expressed across the nervous system and mutations of NF2 gene were originally associated with Neurofibromatosis type 2, that comprises a group of benign neural tumors." (PMID 29415512, 2018). "Neurofibromatosis type 2, the rarer of the two subtypes, involves the loss of the NF2 gene, which encodes for the regulator protein merlin." (PMID 28288694, 2017). "Neurofibromatosis type 2 (NF2) is an autosomal dominant disease that is caused by loss-of-function mutations in the NF2 gene located on chromosome 22q12.2." (PMID 26709712, 2016).
neurofibromatosis type 2 (continued). "Neurofibromatosis type 2 is an autosomal dominant disease caused by mutation of chromosome 22 band q 11-13.1, called the NF2 gene (neurofibromin 2) or merlin gene (moesinezrin-radixin-like protein)." (PMID 27738538, 2016). "NF2 mutations are found in different pathologies, especially in malignant mesothelioma and Neurofibromatosis type 2." (PMID 27929432, 2016). "Higher incidence of spinal ependymomas in patients with neurofibromatosis type 2 and frequent of loss of the NF2 gene in SEPN have been reported in numerous studies." (PMID 25909290, 2015). "Mutations in the Nf2 gene origin an autosomal dominant multiple syndrome called neurofibromatosis type 2,1 leading to merlin loss and determining the transformation of Schwann cells (SCs) into a form of benign tumor called schwannoma." (PMID 27551454, 2015). "The tumour suppressor Merlin, encoded by the gene NF2, is frequently mutated in the autosomal dominant disorder neurofibromatosis type II, characterised primarily by the development of schwannoma and other glial cell tumours." (PMID 26258444, 2015). "Constitutional mutations in the NF2 gene cause an autosomal-dominant disorder (neurofibromatosis type 2) affecting about 1 in 33,000 people, and characterized by the development of tumors primarily affecting the nervous system." (PMID 24393766, 2014). "Mutations in the NF2 gene are causative for the autosomal-dominant disease Neurofibromatosis Type 2 (NF2)." (PMID 25012216, 2014). "Neurofibromatosis type 2 (NF2) is an autosomal dominant disorder that predisposes affected individuals to several types of cerebral and spinal tumors." (PMID 24980480, 2014). "Mutagenic loss of the NF2 tumor suppressor gene encoded protein merlin is known to provoke the hereditary neoplasia syndrome, Neurofibromatosis type 2 (NF2)." (PMID 25012216, 2014). "NF2 mutations in neurofibromatosis 2 can either be germline (70%) or somatic mosaic (30%), the latter referring to mutations present in only a subset of cells." (PMID 24393766, 2014). "Inactivating germline mutations in the tumor suppressor gene NF2 cause the hereditary syndrome neurofibromatosis 2, which is characterized by the development of neoplasms of the nervous system, most notably bilateral vestibular schwannoma." (PMID 24393766, 2014). "Only ~5% of neurofibromatosis 2 patients have constitutional missense mutations and these types of mutations are typically associated with a milder version of NF2." (PMID 24393766, 2014). "This is especially important because of the morbidity and mortality associated with neurofibromatosis 2, and because many agents that impact NF2-related pathways are already available." (PMID 24393766, 2014). "Neurofibromatosis type 2 (NF2) is an autosomal dominant syndrome caused by mutations in the NF2 gene on chromosome 22q12.2." (PMID 22436304, 2012). "Neurofibromatosis type 2 is a dominantly inherited tumour predisposition syndrome caused by mutations in the NF2 gene on chromosome 22." (PMID 19545378, 2009). "The distinction of hybrid tumors (more precisely HNS) is especially important in SWN forms outside the neurofibromatosis type 2 (NF2) spectrum (NF2-SWN), where major diagnostic criteria are less well defined, making histological differentiation even more significant." (PMID 41247561, 2025). "Neurofibromatosis Type 2 (NF2) is caused by mutations in the NF2 gene located on chromosome 22." (PMID 40764996, 2025). "Neurofibromatosis type 2 and schwannomatosis may share the same trigger—loss-of-function mutations in the NF2 gene." (PMID 40940747, 2025). "Although these tumors are frequently associated with neurofibromatosis type 2 (NF2), they may also arise idiopathically, and their pathogenesis remains unclear." (PMID 39742186, 2024). "Although these tumors are frequently associated with neurofibromatosis type 2 (NF2), they may also arise idiopathically, and their pathogenesis remains poorly understood." (PMID 39742186, 2024).
neurofibromatosis type 2 (continued). "However, in about five percent of the cases, they arise as a hallmark manifestation of a genetic germline mutation, formerly called neurofibromatosis type 2 and recently renamed to NF2-related schwannomatosis (NF2)." (PMID 37627117, 2023). "Finally, we identify specific genes where modification of uORFs likely represents an important disease mechanism, and report a novel uORF frameshift variant upstream of NF2 in neurofibromatosis." (PMID 32461616, 2020). "Merlin is encoded by the NF2 gene, mutations in which cause type 2 neurofibromatosis in humans." (PMID 31454940, 2019). "Similar to cytogenetic analysis, these studies identified NF2 mutations as the predominant alteration in both spontaneous (~60%) and Neurofibromatosis syndrome associated (~40%) of tumors, at a frequency of 43% in low grade, and nearly 80% in high grade tumors." (PMID 31970090, 2019). "Type 2, which affects 10% of patients, is associated with an abnormality of the NF2 gene, formerly called central neurofibromatosis or bilateral acoustic neurofibromatosis; however, this mainly affects the central nervous system, rather than the gastrointestinal tract." (PMID 25295078, 2014). "A single case (0.40%) was associated with neurofibromatosis type 2 (NF2)." (PMID 24459428, 2013). "Mutations in NF2 are associated with the autosomal dominant disorder neurofibromatosis type 2." (PMID 24236197, 2013). "Association with neurofibromatosis is possible in 10% of cases and may be related to the type II neurofibromatosis gene (NF2)." (PMID 24381595, 2013). "It occurs mostly in 5 - 15 year old children in form isolated or diffuse; the diffuse form may be associated with neurofibromatosis type 2 (NF2)." (PMID 29147294, 2012). "However, it can also present as multiple lesions, particularly in association with syndromes such as neurofibromatosis type-2 and schwannomatosis, which are linked to genetic mutations in the NF2 gene and the tumor suppressor genes SMARCB1 and LZTR1, respectively." (PMID 40575212, 2025). "NF2-related schwannomatosis (NF2) (formerly Neurofibromatosis type 2) is an autosomal dominant genetic disorder caused by variants in the NF2 gene located on the long arm of chromosome 221–3." (PMID 37087513, 2023). "Neurofibromas are frequently seen in neurofibromatosis (most often type 1 (NF1) but also sporadically in NF2) and often involve peripheral nerves." (PMID 39847050, 2025). "Historically, several reports have associated neurofibromatosis with macrodactyly (primarily affecting NF1 and, even more rarely, NF2)." (PMID 40126231, 2025). "Gradually, the differences in clinical presentation from NF1, led to the labelling of NF2-SWN as bilateral acoustic or central neurofibromatosis based primarily on work at the National Institutes of Health (NIH) in Maryland USA." (PMID 41160189, 2025). "The discovery of the NF2 gene in 1993, definitively distinguished NF2-SWN as a separate disorder from neurofibromatosis." (PMID 41284083, 2025). "Neurofibromatoses are a class of autosomal dominant diseases, divided into Neurofibromatosis type 1 (NF1; OMIM 162200), Neurofibromatosis type 2 (NF2) and Schwannomatosis." (PMID 40402550, 2025). "Neurocutaneous syndromes, known as phakomatoses, encompass a diverse group of congenital conditions affecting the nervous system and skin, with neurofibromatosis type 1 (NF1) and neurofibromatosis type 2 (NF2) among the most clinically significant." (PMID 40843672, 2025). "Sixty-seven patients (8.1%) had documented CPS, with the most prevalent being neurofibromatosis type 1 (NF-1; N=25), followed by tuberous sclerosis (N=10), neurofibromatosis type 2 (NF-2; N=7), and Li-Fraumeni syndrome (N=7)." (PMID 39974082, 2025). "This sustained tumor shrinkage is observed in both benign and malignant tumors associated with different neurofibromatosis subtypes, including NF1, NF2, and schwannomatosis, highlighting the drug’s broad therapeutic potential." (PMID 40725763, 2025).
neurofibromatosis type 2 (continued). "Here, we report the generation of a conditional zebrafish model of neurofibromatosis established by an inducible genetic knockout of nf2a/b, the zebrafish homolog of human NF2." (PMID 38712289, 2024). "Ten children (12%) were diagnosed with NF2-related schwannomatosis (formerly neurofibromatosis type 2 [NF2]) due to clinical characteristics and/or a germline mutation in the NF2 gene." (PMID 39713042, 2024). "Schwann cell tumors are the most common cancers of the peripheral nervous system and can arise in patients with neurofibromatosis type-1 (NF-1) or neurofibromatosis type-2 (NF-2)." (PMID 38216572, 2024). "In alignment with these findings, variable NF2 transcripts were observed in patients with neurofibromatosis type 2, as well as in patients with mesothelioma." (PMID 38879686, 2024). "Neurofibromatosis Type 2 (NF-2) is a dominantly inherited genetic disorder that results from mutations in the tumor suppressor gene, neurofibromin 2 (NF2) gene." (PMID 38712289, 2024). "Here, we report the generation of a conditional zebrafish model of neurofibromatosis established by inducible genetic knockout of nf2a/b, the zebrafish homologs of human NF2." (PMID 39415595, 2024). "Two of the four patients had a unilateral tumor, while the other two had a bilateral tumor with the involvement of the internal auditory canal and cerebellopontine angle (neurofibromatosis type 2 (NF2))." (PMID 38892753, 2024). "Genetic alterations in NF2 are likely the basis for neurofibromatosis type 2, which is characterized by the formation of vestibular schwannomas." (PMID 38879686, 2024). "In the context of neurofibromatosis type 2, MPP1 can bind to the FERM structural domain of the NF2 protein, a tumor suppressor gene encoded by the NF2 gene, potentially leading to a tumor-suppressive effect." (PMID 38169731, 2023). "Four (6.9%) patients had a cancer predisposition syndrome in this cohort, including Li–Fraumeni syndrome (n = 1), neurofibromatosis (NF) type 1 (n = 2) and NF2 (n = 1)." (PMID 37568669, 2023). "For patients with neurofibromatosis type 2 (NF2), maintaining an independent state of living is important." (PMID 37599081, 2023). "We report partial response (PR) to novel therapy with selumetinib in a patient with neurofibromatosis type 2 (NF2)." (PMID 38058737, 2023). "Although it shares its name with NF1, neurofibromatosis type 2 (NF2) is a completely different clinical entity." (PMID 38139220, 2023). "Neurofibromatosis type 2 (NF2) and schwannomatosis (SWN) are genetically distinct tumor predisposition syndromes with overlapping phenotypes, of whom diagnostic criteria have been recently updated." (PMID 37046591, 2023). "NF2 is named after neurofibromatosis type 2, which is a genetic condition in which benign tumors grow along the nerves responsible for hearing and balance; mutations in the NF2 gene were found to cause the disease." (PMID 38001599, 2023). "To date, three neurofibromatosis have been described: neurofibromatosis type 1 (NF1, or von Recklinghausen disease), neurofibromatosis type 2 (NF2), and schwannomatosis (NF3)." (PMID 36899941, 2023). "The process of membrane “anchoring” of the Hippo pathway core kinases utilizes multiple intermediary proteins like Merlin/NF2 (neurofibromatosis type 2) employing Kibra/WWC1/2 proteins." (PMID 35011721, 2022). "Multiple tumors are a hallmark of neurofibromatosis type 1(NF1) and related forms, NF2-related-schwannomatosis (formerly NF2) or SMARCB1/LZTR1-related schwannomatoses." (PMID 35741273, 2022). "Neurofibromatosis type 2 (NF2, also known as central neurofibromatosis) is an autosomal dominant disorder that is distinct from NF1 on both genetic and clinical grounds." (PMID 35320498, 2022).
neurofibromatosis type 2 (continued). "The two most common forms are NF1 (peripheral neurofibromatosis, also known as Recklinghausen’s disease), followed by NF2 (central neurofibromatosis)." (PMID 35204451, 2022). "The three forms of neurofibromatosis, namely NF1, NF2, and SWN are caused by distinct mutations in specific genes." (PMID 35053664, 2022). "Nf2, the product of the gene responsible for the disease neurofibromatosis type 2,33 is pivotal for embryo development, including the development of NC34, 35 and oral structures." (PMID 34697858, 2021). "Neurofibromatosis is comprised of 3 distinct diseases, as follows: neurofibromatosis type 1 (NF1: Von Recklinghausen disease), neurofibromatosis type 2 (NF2), and schwannomatosis." (PMID 34670599, 2021). "Neurofibromatosis type 2 (NF2) is a rare autosomal dominant disorder characterized by the development of multiple nervous system tumors due to mutation in the NF2 tumor suppressor gene." (PMID 33604573, 2021). "Neurofibromatosis type 1 (NF1), neurofibromatosis type 2 (NF2) and schwannomatosis (SWN) are genetic disorders that predispose to the development of nerve sheath tumours." (PMID 33903738, 2021). "There are three forms of NF: neurofibromatosis type 1 (NF1), neurofibromatosis type 2 (NF2), and schwannomatosis." (PMID 33669386, 2021). "As a group of slowly progressive autosomal-dominant syndromes, NF is classified into neurofibromatosis type 1 (NF1), neurofibromatosis type 2 (NF2), and schwannomatosis." (PMID 34604034, 2021). "Neurofibromatosis type 1 (NF1), neurofibromatosis type 2 (NF2) and schwannomatosis (SWN) are rare conditions with pronounced variability of clinical expression." (PMID 33903738, 2021). "Neurofibromatosis type II (NF2), previously known as “central neurofibromatosis”, demonstrates a predilection for “central” intracranial and spinal lesions, most characteristically vestibular schwannomas." (PMID 31161239, 2020). "In 1987, a National Institutes of Health (NIH) neurofibromatosis working group delineated distinct diagnostic criteria for NF1 and NF2 based on genetic linkage and clinicopathologic analysis." (PMID 31161239, 2020). "Despite its nomenclature as a neurofibromatosis syndrome, NF2 only rarely presents with pure neurofibromas." (PMID 31161239, 2020). "In the current study, the effect of neurofibromatosis on quality of life was examined by type of NF (NF1 and NF2); six studies were conducted in neurofibromatosis type 1 and sex in neurofibromatosis type 2." (PMID 31189476, 2019). "Published data on humans report either mutations of Guanine nucleotide-binding protein Gq subunit α (GNAQ), as in uveal melanoma, or inactivation of NF2/merlin, as in the tumor-prone neurofibromatosis syndrome." (PMID 28045433, 2017). "Upstream of the core kinase cassette is the tumor suppressor Merlin (moesin-ezrin-radixin-like protein), which is inactivated in Neurofibromatosis type 2 (NF2)." (PMID 28464980, 2017). "Of the fifteen cases reviewed, thirteen had unilateral sporadic vestibular schwannoma while two had Neurofibromatosis type 2 (NF2)." (PMID 27174775, 2017). "Given the relatively frequent finding of MPNST in NF1 and the rare occurrence of this entity in NF2, it is reasonable to assume that these authors have registered neurofibromatosis patients who would currently be diagnosed as having NF1." (PMID 29214122, 2017). "Angiomotin (AMOT) is a family of proteins found to be a component of the apical junctional complex of vertebrate epithelial cells and is recently found to play important roles in neurofibromatosis type 2 (NF-2)." (PMID 28052036, 2017). "The tumor suppressor protein merlin is mutated in the most frequent hereditary tumor syndrome of the central and peripheral nervous system—Neurofibromatosis type 2 (NF2)." (PMID 27467574, 2016). "We report the clinicopathological features of these hybrid nerve sheath tumors in patients with neurofibromatosis type 2 (NF2)." (PMID 26709712, 2016).